PGAM1 (phosphoglycerate mutase 1)
Diseases named in the same sentence as PGAM1 in open-access papers (continued):
Sharing a sentence is not in itself a finding about the gene and the disease.
triple-negative breast carcinoma (2 papers, 2025 to 2026). An invasive breast carcinoma which is negative for expression of estrogen receptor (ER), progesterone receptor (PR), and human epidermal growth factor receptor 2 (HER2). "In triple-negative breast cancer, PGAM1 is identified as a novel target that exhibits an antitumor effect via the regulation of immunocyte infiltration." (PMID 40046063, 2025). "In triple-negative breast cancer (TNBC), knockdown of YBX1 inhibited the expression of glycolytic genes (ENO1, SLC2A6, LDHA, PFKP, PGAM1, and GPI) and downregulated the expression of EMT-related genes and tumor migration and invasion." (PMID 41507134, 2026).
Alzheimer disease (1 paper, 2020). A progressive, neurodegenerative disease characterized by loss of function and death of nerve cells in several areas of the brain leading to loss of cognitive function such as memory and language. "PGAM1 is highly susceptible to oxidative stress, which leads to the inhibition of glycolysis and is easily oxidized in conditions of neurological disease, such as Alzheimer’s disease and hypoxic damage." (PMID 33050051, 2020).
astrocytomas (1 paper, 2019). "PGAM1 is involved in tumor cell glycolysis and biosynthesis, and this protein had elevated expression levels in high-grade astrocytomas." (PMID 31620163, 2019).
autoimmune disease (1 paper, 2024). A disorder resulting from loss of function or tissue destruction of an organ or multiple organs, arising from humoral or cellular immune responses of the individual to their own tissue constituents. "Additionally, anti-PGAM1 antibodies have been observed in various autoimmune diseases of the CNS." (PMID 38652420, 2024).
bladder carcinomas (1 paper, 2024). "Results demonstrated PGAM1 is aberrantly overexpressed in most tumors compared to normal tissues, and this overexpression is associated with poor prognosis, advanced tumor staging, and aggressive clinical phenotypes in multiple cancers including UVM, lung, breast and bladder carcinomas." (PMID 38434965, 2024).
breast tumors (1 paper, 2021). "However, the expression of PGAM1 has been found to be decreased in cells resistant to methotrexate, which can change glucose metabolism and be involved in the mechanism of multiple drug resistance in breast tumors." (PMID 33668689, 2021).
colorectal tumor (1 paper, 2024). "Proteins that regulate glycolysis (PGK1, PGAM1, ENO1, PKM, TKT), ammonia detoxification (GLUD1), and other metabolic pathways (LDHA, GAPDH, MDH2) were reported to be differentially expressed in mouse xenograft colorectal tumor models with different radio- responsiveness." (PMID 38410100, 2024).
endotoxemia (1 paper, 2024). "First, Pgam1 and Dusp1 have emerged as potential biomarkers for myocardial dysfunction in endotoxemia, offering fresh perspectives on the biomolecular basis of this affliction." (PMID 39659576, 2024). "Targeting the Pgam1-Dusp1 axis represents a promising therapeutic strategy for improving cardiac outcomes in patients with endotoxemia." (PMID 39659576, 2024). "In conclusion, our findings suggest that elevated Pgam1 expression in conjunction with dephosphorylated Dusp1 constitutes potential molecular underpinnings of myocardial dysfunction in endotoxemia, mainly through the perturbation of MQC." (PMID 39659576, 2024). "To translate our cellular findings into an animal experiment, we employed cardiomyocyte-specific Pgam1 knockout (Pgam1cko) mice subjected to LPS-induced endotoxemia." (PMID 39659576, 2024). "Consequently, therapeutically targeting the Pgam1/Dusp1 axis emerges as a promising strategy to ameliorate cardiac function in endotoxemia-afflicted patients." (PMID 39659576, 2024). "Our research seeks to clarify the regulatory function of Pgam1 in Dusp1 dephosphorylation and subsequent degradation, potentially disrupting MQC in cardiomyocytes and exacerbating endotoxemia-induced myocardial injury." (PMID 39659576, 2024). "The interaction between increased Pgam1 and Dusp1 fosters dephosphorylation and subsequent degradation of Dusp1, exacerbating the impairment in MQC and contributing to myocardial dysfunction in endotoxemia." (PMID 39659576, 2024).
familial Alzheimer disease (1 paper, 2025). A degenerative disease of the brain that causes gradual loss of memory, judgment, and the ability to function socially. "Furthermore, integration with data from familial Alzheimer's disease indicated ALDOA, ENO1, PKM and PGAM1 are all upregulated in the early to middle stages of disease onset." (PMID 40491829, 2025).
Glucose intolerance (1 paper, 2022). Glucose intolerance (GI) can be defined as dysglycemia that comprises both prediabetes and diabetes. "We have not fully elucidated the mechanisms by which Adipo-Pgam1 KO mice show glucose intolerance along with normal thermogenic response." (PMID 35521515, 2022).
hilar cholangiocarcinoma (1 paper, 2012). A cholangiocarcinoma that arises from the junction, or adjacent to the junction, of the right and left hepatic ducts. "Intense PGAM-1, HSPD1, PDIA3 and SSP411 cytoplasmic immunoreactivity was observed in both hilar cholangiocarcinoma and intrahepatic cholangiocarcinoma." (PMID 23118872, 2012).
invasive ductal carcinoma (1 paper, 2017). "Our present results showed that in a statistical average of 100 cases of invasive ductal carcinoma an increase of some key glycolytic enzymes occurred, namely: ALDOA, G3P KPYM, PGK1, and LDHA, while no relevant increase was observed for other glycolytic enzymes (i.e., ENOA, PGAM1, TPIS)." (PMID 28686225, 2017).
ischemia (1 paper, 2020). A hypoperfusion of the BLOOD through an organ or tissue caused by a PATHOLOGIC CONSTRICTION or obstruction of its BLOOD VESSELS, or an absence of BLOOD CIRCULATION. "Treatment with Tat-PGAM1 significantly reduced the phagocytic form of microglia, indicating reduced inflammatory responses in the spinal cord after ischemia as compared to the Tat peptide- and Control-PGAM1-treated groups." (PMID 33050051, 2020). "The IL-1β in the Tat peptide- and Control-PGAM1-treated groups transiently increased at 24 h after ischemia and decreased 72 h after ischemia, when compared to the basal level." (PMID 33050051, 2020). "NeuN immunohistochemistry releveled that Tat-PGAM1 protected neurons from ischemic damage in the spinal cord 72 h after ischemia, and we confirmed that this effect was maintained by 7 days after ischemia." (PMID 33050051, 2020). "Treatment with Tat-PGAM1 significantly alleviated the transient increases in pro-inflammatory cytokines after ischemia and reduced the inflammatory response." (PMID 33050051, 2020). "In addition, Tat-PGAM1 reduces the microglial activation and subsequent increases in pro-inflammatory cytokines after ischemia." (PMID 33050051, 2020). "In addition, we observed the treatment with Tat-PGAM1 significantly reduced the neurological deficits induced by spinal cord ischemia 24 and 72 h after ischemia." (PMID 33050051, 2020). "After ischemia induction in the spinal cord, Tat-PGAM1 treatment significantly improved ischemia-induced neurological impairments and ameliorated neuronal cell death in the ventral horn of the spinal cord 72 h after ischemia." (PMID 33050051, 2020). "Collectively, our study investigated the effects of Tat-PGAM1 on H2O2-induced oxidative stress in NSC34 cells and ischemia-induced cell damage." (PMID 33050051, 2020). "In addition, Tat-PGAM1, but not Control-PGAM1, significantly decreased microglial activation and secretion of pro-inflammatory cytokines, such as interleukin (IL)-1β, IL-6, and tumor necrosis factor (TNF)-α induced by ischemia in the ventral horn of the spinal cord." (PMID 33050051, 2020).
ischemic stroke (1 paper, 2026). A stroke disorder caused by obstruction of blood flow to the brain, due to thrombotic (local blood clot formation) or embolic (due to a blood clot or other material traveling from another site) event. "Interestingly, 203 upregulated and 212 downregulated genes, including Krt5, Krt14, Col17a1, and Pgam1‐ps1, were shared between EC‐specific KO and Vasculotide‐treated mice, indicating mutual pathways underlying the endothelial EphA4/Tie2 axis following ischemic stroke." (PMID 41164967, 2026).
kidney tumor (1 paper, 2018). "PGAM1 was elevated in mouse kidney tumor caused by up-regulated mTOR due to Tsc2 exon 3 deletion (Tsc2del3/+) compared with its adjacent kidney tissue." (PMID 29362480, 2018). "In this study, we identified mTOR as a stimulator of PGAM1 expression in cell lines, Tsc2 mutant mouse kidney tumor sample and human NSCLC tissues." (PMID 29362480, 2018).
leiomyosarcoma (1 paper, 2025). An uncommon, aggressive malignant smooth muscle neoplasm, usually occurring in post-menopausal women. "Consistent with the pathological diagnosis of leiomyosarcoma, 53KOLS cells expressed Pgam2 considerably higher than Pgam1." (PMID 40707487, 2025).
lung fibrosis (1 paper, 2025). "Inhibition of the PGAM1-Chk1 interaction improves physiological parameters during aging and inhibits lung fibrosis in mouse models." (PMID 41392167, 2025). "Overall, both chemical and genetic interference with the PGAM1-Chk1 axis alleviated pulmonary fibrosis in vivo, which is an aging-related disease." (PMID 41392167, 2025). "Consistently, chemical inhibition or genetic manipulation of PGAM1-Chk1 binding mitigated lung fibrosis, indicating that PGAM1-Chk1 interference is a promising senolytic for relevant disorders in aging." (PMID 41392167, 2025). "As FOXM1 accumulates in aged tissues, chemical or genetic abrogation of PGAM1-Chk1 binding impedes the protective role of FOXM1 in SnCs, inducing the death of senescent cells and alleviating dysfunction, including lung fibrosis, in vivo, indicating its potential efficacy as senotherapy." (PMID 41392167, 2025).
malignant glioma (1 paper, 2024). A grade III or grade IV glioma arising from the central nervous system. "Emodin was found to be a potent inhibitor of phosphoglycerate mutase 1 (PGAM1) and inhibited the enzyme activity by 50% (IC50) at 19.82 μM in U-87 malignant glioma cells or 17.08 μM in patient-derived X01 cells." (PMID 39770078, 2024).
mastitis (1 paper, 2022). Inflammation of breast tissue during lactation or postpartum due to an obstructed duct or infection. "When mastitis developed (T1/C1), GPI, TPI1, GAPDH, PGK1, PGAM1, ENO1, and PKM in the glycolysis/gluconeogenesis pathway were upregulated, which promoted pyruvate synthesis with large amounts of ATP production." (PMID 36335251, 2022).
myocardial infarction (1 paper, 2024). Gross necrosis of the myocardium, as a result of interruption of the blood supply to the area, as in coronary thrombosis. "In a murine myocardial infarction model, Pgam1 levels are elevated in ischemic hearts, while Pgam1 knockout improves cardiac function and prevents remodeling by suppressing inflammation, apoptosis, and fibrosis." (PMID 39659576, 2024).
neuroblastoma (1 paper, 2020). Neuroblastoma (NB) is the most common solid, extracranial childhood tumor. "In the present study, we investigated the effects of Tat-PGAM1 and its control protein (Control-PGAM1) against oxidative stress in the NSC34 cell line, which is a hybrid of mouse neuroblastoma cells and motor neurons from the spinal cord of mouse embryos." (PMID 33050051, 2020).
nevus (1 paper, 2022). Nevus (or naevus, plural nevi or naevi, from nævus, Latin for "birthmark") is the medical term for sharply circumscribed[1] and chronic lesions of the skin or mucosa. "The levels of ENO1 and PGAM1 in 12 tumor samples and nevus tissues were determined using Western blotting." (PMID 35925486, 2022). "The results showed that compared with that in normal benign nevus tissue samples, the levels of ENO1 and PGAM1 in SKCM tissue samples were significantly higher." (PMID 35925486, 2022).
Parkinson disease (1 paper, 2017). A progressive degenerative disorder of the central nervous system characterized by loss of dopamine producing neurons in the substantia nigra and the presence of Lewy bodies in the substantia nigra and locus coeruleus. "Five to seven pQTL were observed for phosphoglycerate mutase 1 (PGAM1), the putative Parkinson disease autosomal recessive early onset 7 variant 1 (PARK7), triose phosphate isomerase (TPI1), peroxiredoxin 4 (PRDX4), malate dehydrogenase 1 (MDH1) and 3-hydroxyanthranilate 3,4-dioxygenase (HAAO)." (PMID 28424047, 2017).
phenylketonuria (1 paper, 2020). Phenylketonuria (PKU) is the most common inborn error of amino acid metabolism and is characterized by mild to severe mental disability in untreated patients. "In addition, PGAM1 levels are decreased in the brains of mice models of phenylketonuria and in the hippocampus of mice exposed to copper toxicity." (PMID 33050051, 2020).
renal carcinoma (1 paper, 2023). A carcinoma arising from the epithelium of the renal parenchyma or the renal pelvis. "Furthermore, pharmacogenomic analysis of renal cancer cell lines indicated that inactivation of PGAM1 was associated with increased sensitivity to specific small-molecule drugs." (PMID 37847178, 2023). "Based on the hypothesis that PGAM1 expression might be associated with the tumor microenvironment of renal cancer and differ significantly in macrophages, we assessed the correlation of macrophage subtypes (M0, M1, and M2) with PGAM1." (PMID 37847178, 2023). "To assess the transcriptome of PGAM1 in renal cancer at the single-cell level and to explore the heterogeneity of different cell types in the renal cancer microenvironment, we conducted an analysis of two publicly available single-cell RNA-sequencing databases (GSE159115 and GSE121636)." (PMID 37847178, 2023). "The function of the PGAM1 gene in renal cancer remains unknown." (PMID 37847178, 2023).
spinal cord ischemia (1 paper, 2020). Reduced blood flow to the spinal cord which is supplied by the anterior spinal artery and the paired posterior spinal arteries. "We also examined the effects of Tat-PGAM1 and Control-PGAM1 in rabbits to determine their neuroprotective potential against spinal cord ischemia." (PMID 33050051, 2020).
thyroid cancer (1 paper, 2025). "Key metabolic regulators such as IDH1, PGAM1, NDUFS3, and LDHB were identified among these common genes, suggesting their central role in thyroid cancer metabolism." (PMID 40861812, 2025). "For instance, several genes such as IDH1 and PGAM1 displayed consistent alterations at the transcript, protein, and metabolite levels, indicating their critical role in reprogramming energy pathways like glycolysis and the TCA cycle in thyroid cancer." (PMID 40861812, 2025).
type 2 diabetes mellitus (1 paper, 2025). A type of diabetes mellitus that is characterized by insulin resistance or desensitization and increased blood glucose levels. "PGAM1, which plays a crucial role in aerobic glycolysis, is a physiologically and pathologically important enzyme and a promising therapeutic target for cancer, type 2 diabetes, and senescence." (PMID 41080753, 2025). "PGAM1 is an attractive therapeutic target for cancer, type 2 diabetes, and senescence." (PMID 41080753, 2025). "Moreover, PGAM1 plays a crucial role in glycolysis, catalyzing the conversion of 3-phosphoglycerate to 2-phosphoglycerate, and is a promising target in cancer, type 2 diabetes and senescence." (PMID 41080753, 2025). "Moreover, PGAM1 is considered as an attractive target for type 2 diabetes and senescence." (PMID 41080753, 2025).
Uterine leiomyoma (1 paper, 2018). The presence of a leiomyoma of the uterus. "The expression of PGAM1 was suppressed by either rapamycin or ectopic expression of human TSC2 cDNA in Tsc2-null Eker rat uterine leiomyoma cell line (ELT3)." (PMID 29362480, 2018).
uveal melanoma (1 paper, 2024). A melanoma derived from melanocytes of the uveal tract. "However, the expression and function of PGAM1 in uveal melanoma (UVM) are unknown and systematic analysis is lacking." (PMID 38434965, 2024).
ZIKV infection (1 paper, 2022). "Previously, we detected PGAM1, a key regulator of glycolysis and gluconeogenesis pathways, as significantly up-regulated by ZIKV infection in HSerC." (PMID 35215967, 2022).